BMP4 (bone morphogenetic protein 4)
Diseases named in the same sentence as BMP4 in open-access papers (continued):
Sharing a sentence is not in itself a finding about the gene and the disease.
microphthalmia (18 papers, 2009 to 2025). Congenital or developmental anomaly in which the eyeballs are abnormally small. "BMP4 variants have been reported to be associated with syndromic microphthalmia (MCOPS6, OMIM 607932)." (PMID 34926457, 2021). "In previous studies, variants in BMP4 have been mainly reported to be associated with microphthalmia, anophthalmia, coloboma (MAC) and anterior segment dysgenesis (ASGD) in human." (PMID 34926457, 2021). "Previously, truncations in BMP4 were reported to cause microphthalmia, anophthalmia, and coloboma (MAC) and anterior segment dysgenesis (ASGD), phenotypes that in contrast to those of pathologic myopia." (PMID 34926457, 2021). "The role of BMP4/7 heterodimers in eye development is likely conserved in humans since Bmp4 or Bmp7 are co-expressed in the developing human eye, and mutations in either gene are associated with anophthalmia, microphthalmia and chorioretinal coloboma." (PMID 31566563, 2019). "BMP4 is a growth factor known to contribute to eye development in animals, and gene variants in humans have been linked to microphthalmia/anophthalmia as well as CAKUT." (PMID 30568244, 2019). "The majority of documented BMP4 loss-of-function variants have severe ocular anomalies, including anophthalmia, microphthalmia, and anterior chamber abnormalities with congenital glaucoma." (PMID 30568244, 2019). "Mice models with bmp4 loss-of-function variants have features including microphthalmia, craniofacial anomalies, polydactyly and congenital anomalies of the kidney and urinary tract (CAKUT)." (PMID 30568244, 2019). "BMP4 is located in 14q22-q23, where recurrent interstitial deletions have been associated with anophthalmia-microphthalmia." (PMID 20057906, 2009). "Recently, mutations in BMP4 mutations have been detected in patients with anophthalmia-microphthalmia." (PMID 20057906, 2009). "Diseases associated with BMP4 include microphthalmia and orofacial cleft." (PMID 40496916, 2025). "In addition, we also identified a monoallelic mutation in BMP4, which has been mostly associated with microphthalmia or facial clefts." (PMID 32883240, 2020). "Humans with loss-of-function variants in BMP4 have previously been described with highly variable manifestations, including anophthalmia/microphthalmia, syndactyly and structural brain anomalies including thinning of the corpus callosum and widened cerebral sulci." (PMID 30568244, 2019). "Interestingly, heterozygous BMP4 mutations have been associated with microphthalmia, microcornea, coloboma, retinal dystrophy, and tilted optic disc." (PMID 21750680, 2011). "BMP4 is a growth factor that has an important role during embryonic development as well as ocular development, and other pathogenic variants of BMP4 usually result in severe developmental abnormalities such as anophthalmia/microphthalmia, structural brain anomalies, and syndactyly." (PMID 35741851, 2022). "Heterozygous Bmp4+/− mice exhibit anophthalmia-microphthalmia, failure of lens induction, anterior segment dysgenesis, and retinal and optic nerve aplasia." (PMID 39152126, 2024). "Additionally, one gene, RMND1, is novel for the phenotype of polymicrogyria whilst BMP4 is a putative novel gene for Kapur-Toriello syndrome which, if confirmed, would extend the phenotypic range of this gene from its current association with microphthalmia and clefting syndrome." (PMID 37946251, 2023). "This is in agreement with its position downstream of bone morphogenetic protein 4 (BMP4), mutations in which cause microphthalmia in humans and mice." (PMID 24681822, 2014). "In that study, the c.751C>T variation in BMP4 was present in a patient with microphthalmia, as well as in his healthy brother, and possibly in one of his normal parents." (PMID 20057906, 2009).
microphthalmia (continued). "Mutations in several genes have been reported in patients with microphthalmia and/or coloboma, including BMP4 (OMIM 112262), VSX2 (CHX10; OMIM 142993), CRYBA4 (OMIM 123631), OTX2 (OMIM 600037), RAX (OMIM 601881), SIX6 (OMIM 606326), and SOX2 (OMIM 184429)." (PMID 20057906, 2009). "A similar search of DR17 using the term microphthalmia resulted in 22 genes significant for the small eyes phenotype: Aldh1a3, Aff4, Bmp4, Cdk4, Cox6b1, Cxcr4, Dync1li1, Eef1d, Fgd1, Gne, Grh12, Mab21l2, Maf, Med13l, Mllt10, Mthfd2, Pex6, Phgdh, Ssr1, Stim1, Tdo2, and Vps26c." (PMID 36737727, 2023). "Deletions of the 14q22-q23 region, which includes BMP4 as well as OTX2, also known to be important for eye development, have been described causing anophthalmia/microphthalmia and also hearing problems, Pierre-Robin sequence, developmental delay and cleft palate." (PMID 30568244, 2019). "Indeed, variants in GDF6 (BMP13), BMP4, and SMOC1 are linked to inferior coloboma and microphthalmia." (PMID 29522511, 2018). "Additionally, compound heterozygous mice for Bmp4 and Bmp2 present with microphthalmia and retinal degeneration." (PMID 29738572, 2018). "Similarly, clinical studies have revealed that individuals with anophthalmia or microphthalmia, combined with sclerocornea, were found to harbor a nonsense mutation in Bmp4." (PMID 39152126, 2024). "Except for BMP4, opposite ocular phenotypes have been associated with mutations in other genes, such as FZD5, in which individuals with the same truncation variant or different eyes of the same individual exhibited either microphthalmia/uveal coloboma or high myopia." (PMID 34926457, 2021). "Similarly, incomplete penetrance and variable expressivity have been observed in families with heterozygous mutations in orthodenticle homeobox 2 (OTX2) or bone morphogenetic protein 4 (BMP4), which are associated with anophthalmia/microphthalmia or severe anterior segment dysgenesis." (PMID 22815627, 2012). "The data presented in this study demonstrated that heterozygous BMP4 truncations contributed to a novel phenotype: pathologic myopia rather than microphthalmia." (PMID 34926457, 2021).
gastric cancer (17 papers, 2011 to 2026). A primary or metastatic malignant neoplasm involving the stomach. "BMP4 (bone morphologic protein 4) was shown to be associated with poorly differentiated gastric cancer and in bone and soft tissue sarcoma." (PMID 21708004, 2011). "CHRDL1, a BMP4 antagonist, has tumor-suppressive effects in breast and gastric cancers, but its role in pancreatic cancer is unclear." (PMID 40837015, 2025). "This is in line with a previous report, which demonstrated that BMP4 is highly expressed in cisplatin-resistant gastric cancer cells and that targeting BMP4 sensitizes these cells to cisplatin." (PMID 35902550, 2022). "Upregulated BMP4 has been reported in gastric cancer, hepatocellular carcinoma and colorectal cancer." (PMID 35902550, 2022). "Collectively, these data demonstrate that low CHRDL1 expression activates Akt, Erk and induces cell proliferation and migration through BMP4 in gastric cancer." (PMID 28423564, 2017). "And we also observed high expression of BMP4 indicated poor survival of gastric cancer patients in TCGA database." (PMID 28423564, 2017). "BMP4 is an autocrine protein whose aberrant secretion can induce tumorigenesis, including gastric cancer." (PMID 28423564, 2017). "Recently, a study showed that BMP-4 is highly expressed in cisplatin-resistant gastric cancer (GC) cell lines." (PMID 24779016, 2014). "Therefore, targeted genetic inhibition of BMP4 expression revealed promising target therapy to improve the prognosis of gastric cancer." (PMID 32489454, 2020). "Further, BMP-4 mRNA is preferentially overexpressed in poorly differentiated gastric cancer, and overexpression of BMP-2/4, -5 or BMPR-IA are all associated with malignancy of oral epithelium and may be involved in the metastasis of oral carcinoma cells." (PMID 22168923, 2011). "Activation of these non-canonical pathways by BMP4 may explain the association between high levels of BMP4 expression and chemotherapy resistance in non-small cell lung cancer and in gastric cancer." (PMID 38689334, 2024). "Thus, low CHRDL1 expression promotes cell metastasis through BMP4 in gastric cancer." (PMID 28423564, 2017). "Since GREM1 functions as an antagonist against both BMP2 and BMP4, its upregulation would result in a general inhibition effect to the BMP signaling pathways in gastric cancer." (PMID 29720137, 2018). "Using mouse models of inflammation-induced gastric cancer, a study reported that at least 20% of CAFs are derived from MSCs of bone marrow, and show the expression of α-SMA, wingless-related integration site 5α (Wnt5α), IL-6, bone morphogenetic protein 4 (BMP4), and DNA hypomethylation." (PMID 37065872, 2023). "Furthermore, BMP4 expression was significantly up-regulated (P = 4.53 × 10− 5; 2.25-fold enrichment) in 197 gastric cancer samples when compared with non-malignant gastric tissues." (PMID 26380657, 2015). "But, most cancer patients had similar expression level of BMP2 and BMP4 as non-cancer patients, indicating that the expression of BMP ligands was not altered in gastric cancer." (PMID 29720137, 2018).
lung cancer (17 papers, 2012 to 2024). A malignant neoplasm involving the lung. "In lung cancer patients BMP-4 genetic variants influenced platinum-based chemotherapy response and prognosis." (PMID 34501309, 2021). "In lung cancer, the downregulation of BMP4 caused by overexpression of miR-200a can inhibit the development and migration ability of tumor cells." (PMID 32226520, 2020). "Our study adds to the existing knowledge the findings that not only both TSP-1 and BMP-4 levels as measured by ELISA in the serum of the patients are decreased in lung cancer, but also that TSP-1 is associated with more advanced lung cancer stages and lymph nodes involvement." (PMID 34501309, 2021). "As a close relative of BMP2, the upregulation of BMP4 has been proven to be strongly associated with EGFR-TKI resistance and fatty acid metabolism in lung cancer." (PMID 34745928, 2021). "The study confirms a role of decreased serum expression of TSP-1 and BMP-4 as the markers of lung cancer, with the lowest TSP-1 concentrations associated with more advanced lung cancer stages and with lymph nodes involvement." (PMID 34501309, 2021). "There is little information regarding the significance of the combination of serum levels of these two proteins, i.e., TSP-1 and BMP-4, and BMP-4 polymorphism in the development and progression of lung cancer." (PMID 34501309, 2021). "Higher expression of BMP-4 mRNAs (2.3 times) in lung cancer than in normal lung tissue has been reported." (PMID 34501309, 2021). "In the BMP-4 knockdown lung cancer cell lines inhibition of cell growth, migration, invasion and metastases formation was observed." (PMID 34501309, 2021). "Even though BMP-4 seems to be promising molecule in lung cancer diagnosis and monitoring, the majority of studies based on tissue expression or genetic examinations." (PMID 34501309, 2021). "BMP-4 serum levels were significantly lower in the patients with lung cancer than in the control group (138.35 ± 62.59 pg/mL vs. 226.68 ± 135.86 pg/mL, p < 0.001)." (PMID 34501309, 2021). "The expression levels of VEGF, BMP2, and BMP4 mRNA were significantly higher (7.1-fold, 25.6-fold, and 2.3-fold, respectively) in lung cancer samples than those in adjacent normal lung tissues." (PMID 34722241, 2021). "The main importance of our study is finding of decreased serum levels of TSP-1 and BMP-4 in lung cancer patients." (PMID 34501309, 2021). "In lung cancer, premature senescence induced by BMP4 mediated Smad signaling pathway decreases cell growth rate in vitro and tumorigenicity in vivo." (PMID 28852126, 2017). "Inhibition of invasion ability and less angiogenic phenotype were also seen in lung cancer cells with BMP4 treatment." (PMID 28852126, 2017). "For instance, in lung we found FOXA2, TBX4 and BMP4, and although the role of LHX6 in lung development is less well defined, it has previously been implicated as a tumour suppressor in lung cancer." (PMID 27562343, 2016). "BMP4 expression levels in murine lung cancer cells were measured by quantitative reverse transcription-PCR (qRT-PCR) and Western blotting." (PMID 26395571, 2015). "Next, to investigate the biological role of Bmp4 repression by miR-200, we depleted BMP4 in 344SQ cells and H157 human lung cancer cells by stable transfection of shRNAs." (PMID 26395571, 2015). "We found that bone morphogenetic protein 4 (BMP4) was decreased in miR-200-overexpressing cells and epithelial-like lung cancer cells." (PMID 26395571, 2015). "In summary, BMP4 functions as a pro-tumorigenic factor in a murine lung cancer model and is regulated by miR-200 and GATA4/6." (PMID 26395571, 2015). "BMP4 functions as a pro-tumorigenic factor in a murine lung cancer model, and its transcription is regulated by miR-200 and GATA4/6." (PMID 26395571, 2015).
lung cancer (continued). "Murine lung cancer cells were transfected with Bmp4 shRNAs, which were then injected into syngeneic mice to measure their tumorigenic and metastatic potential and cultured on Matrigel to study the influence of BMP4 on 3-D acinus formation." (PMID 26395571, 2015). "ZEB1, a transcription suppressor of miR-200, enhanced Bmp4 expression in a low metastatic lung cancer cell line (393P), but miR-200 suppressed Bmp4 expression in 344SQ and 531LN2, which was confirmed by Western blotting." (PMID 26395571, 2015). "Bmp4 knockdown suppressed cancer cell growth, migration, and invasion and inhibited tumorigenesis and metastasis of lung cancer cells when injected into syngeneic mice." (PMID 26395571, 2015). "Newest in vitro studies confirmed the role of BMP-4 in lung cancer progression." (PMID 34501309, 2021). "Moreover, in vitro studies indicated that BMP-4 could be potential therapeutic target in the treatment of lung cancer patients." (PMID 34501309, 2021). "Thus, we propose that BMP4 and its antagonists may be suitable therapeutic targets for the treatment of lung cancer." (PMID 26395571, 2015). "In addition, BMP4 was required for normal acinus formation in Matrigel 3-D culture of murine lung cancer cells, which may be mediated by MYH10, a downstream target of BMP4." (PMID 26395571, 2015). "At present, approximately 20 BMPs have been identified; however, most studies involving BMPs in lung cancer have focused on BMP2, BMP4, and BMP7." (PMID 34745928, 2021). "ACVR2A, ACVR1C, BMP4, and CHRDL2, on the other hand, was found to be commonly co-expressed with BMP5 in bladder, breast and lung cancer." (PMID 31973134, 2020). "To evaluate the importance of FSTL1-BMP4-Smad pathway in lung cancer, we first analyzed the prognostic value of FSTL1, BMP4, Smad4, and p-Smad1/5/8." (PMID 28852126, 2017). "In a lung cancer cell-line model, p38 MAPK activation was required for full activation of the transcriptional potential of Smad1/5, after treatment with BMP-4." (PMID 22299030, 2012). "In the previous studies BMP-4 and TSP-1 in lung cancer patients were mostly studied separately." (PMID 34501309, 2021). "We were not able to find any previous publication in which BMP-4 serum levels were examined in lung cancer patients." (PMID 34501309, 2021). "The roles of BMP4 and BMP7 in lung cancer may be controversial." (PMID 32750747, 2020). "Finally, we identified BMP5 as having significantly differential expression and superior prognostic value, rather than BMP2, BMP4, and BMP7, which have been extensively explored in lung cancer." (PMID 34745928, 2021). "Some researches demonstrate that BMP4 and BMP7 enhance invasion and metastasis of lung cancer while others do not, which may need to be further confirmed." (PMID 32750747, 2020). "Furthermore, BMP4, which plays a crucial role in migration and invasion, was not activated by SERPINE2 knockdown in A549 and PC9 lung cancer cells." (PMID 33317533, 2020).
Anophthalmia (15 papers, 2006 to 2024). Absence of the globe or eyeball. "This is in line with previous findings and supporting the idea that the loss of rx3 and consecutively the loss of cxcr4a is a reason for anophthalmia resulting from induction of bmp4." (PMID 37175759, 2023). "In fact, contrary phenotype due to a BMP4 truncation mutation was reported in one family, where the proband had unilateral anophthalmia, small cornea, and iris and chorioretinal coloboma, while his three family members with the same mutation had high myopia." (PMID 34926457, 2021). "A recent study that included patients with eye abnormalities identified BMP4 mutations in a familial case of anophthalmia, retinal dystrophy, brain malformation, and poly/syndactyly." (PMID 33634051, 2020). "Deletions in BMP4 were associated with bilateral anophthalmia/microphthalmia, in association with hypothyroidism, deafness, developmental delay, and cerebellar and pituitary abnormalities." (PMID 33634051, 2020). "Anophthalmia, the most severe phenotype, is associated with mutations of the Rax, Sox2, Lhx2, BMP-4, and BMP7 genes." (PMID 31817535, 2019). "Here, we induced bmp4 at 8.5 hpf and found a severe form of HPE associated with anophthalmia in 97.5% of the cases, indicating a robust experimental paradigm." (PMID 37175759, 2023). "While it is difficult to make firm conclusion, based on the published literature and our own unpublished data, BMP4 and RAX, in particular, appear to be very rare causes of anophthalmia." (PMID 24498598, 2013). "Deletions of human chromosome 14q, including the BMP4 gene have been identified in patients with anophthalmia." (PMID 17173667, 2006).